GATB (glutamyl-tRNA amidotransferase subunit B)
Description:
Allows the formation of correctly charged Gln-tRNA(Gln) through the transamidation of misacylated Glu-tRNA(Gln) in the mitochondria. The reaction takes place in the presence of glutamine and ATP through an activated gamma-phospho-Glu-tRNA(Gln).
Synonyms: PET112; PET112L; HSPC199; COXPD41
Tractability: PROTAC: ubiquitination databases record sites on it; its protein half-life has been measured.
Gene: Protein-coding gene on chromosome 4 (151,670,458 to 151,761,028, reverse strand). Ensembl gene ENSG00000059691.
Subcellular location: Mitochondrion
Subcellular location (Human Protein Atlas): Mitochondria
Gene Ontology:
Molecular function: glutaminyl-tRNA synthase (glutamine-hydrolyzing) activity; protein binding; carbon-nitrogen ligase activity, with glutamine as amido-N-donor; catalytic activity; ligase activity
Biological process: glutaminyl-tRNAGln biosynthesis via transamidation; mitochondrial translation
Cellular component: glutamyl-tRNA(Gln) amidotransferase complex; mitochondrion
Genetic constraint (gnomAD): Loss-of-function variants: 28 observed, 45.75 expected, observed/expected ratio (o/e) 0.61, 90% interval 0.45 to 0.84. The upper end of that interval is the gene's LOEUF score, 0.84, which puts it in group 3 of 6, group 1 being the genes least tolerant of losing a copy. Missense variants: 571 observed, 584.91 expected, observed/expected ratio (o/e) 0.98, 90% interval 0.91 to 1.05. Synonymous variants: 238 observed, 227.38 expected, observed/expected ratio (o/e) 1.05, 90% interval 0.94 to 1.16.
Homologues: Orthologues: chimpanzee GATB (96% identical), macaque GATB (95% identical), mouse Gatb (85% identical), rat Gatb (83% identical), guinea pig GATB (82% identical), rabbit GATB (80% identical), dog GATB (75% identical), tropical clawed frog gatb (63% identical), zebrafish gatb (60% identical), Drosophila melanogaster GatB (41% identical), Caenorhabditis elegans C39B5.6 (32% identical).
Diseases named in the same sentence as GATB in open-access papers:
GATB is named in the same sentence as 4 diseases in open-access papers, as found by Europe PMC text mining. Sharing a sentence is not in itself a finding about the gene and the disease. The quoted sentences say what the papers report.
autism (1 paper, 2024). Persistent deficits in social interaction and communication and interaction as well as a markedly restricted repertoire of activity and interest as well as repetitive patterns of behavior. "There was a nominally significant set-level association with autism (P = 0.03) that would not remain significant if corrected for multiple testing over all language-related and psychiatric traits, with five genes individually associated at P < 0.05: BMPER, GATB, KCNH5, SNCA, and SYT2." (PMID 39133845, 2024).
deficiencies (1 paper, 2022). "The GATB gene downregulation is shown to be responsible for the respiratory chain enzyme deficiencies, and thus disturbing the mitochondrial function and possesses complications for the much-needed energy intensive physiological mechanisms to dissipate incremental heat load in cattle." (PMID 35986427, 2022).
infection (3 papers, 2013 to 2019). The state of being infected such as from the introduction of a foreign agent such as serum, vaccine, antigenic substance or organism. "SNP-11, SNP-93 and SNP-186 provide three additional cases for the existence of distinctive gatB haplotypes of the wCer2 infection since all three were repeatedly isolated from hosts that were independently microinjected." (PMID 24376534, 2013). "The infection was validated by sequencing the PCR amplicons from the ftsZ, gatB, DE, and PE genes." (PMID 31161026, 2019).
GATB also shares sentences with these, for which no sentence is quoted: lactic acidosis (1 paper).